HIPK2 (homeodomain interacting protein kinase 2)
Diseases named in the same sentence as HIPK2 in open-access papers (continued):
Sharing a sentence is not in itself a finding about the gene and the disease.
ovarian carcinoma (9 papers, 2009 to 2023). A malignant neoplasm originating from the surface ovarian epithelium. "For conceptual novelty, exogenous HIPK2 should offer a valuable and promising new treatment option to circumvent inhibition of apoptosis for women with chemo-resistant ovarian cancer." (PMID 28107201, 2017). "Other genes that were strongly increased in the ovarian cancer cell lines were HIPK2 and PLAGL1." (PMID 31344863, 2019). "MiR-27a modulated MDR1/P-glycoprotein expression in human ovarian cancer cells by targeting HIPK2 and Down-regulation of miR-27a might reverse multidrug resistance of esophageal squamous cell carcinoma through regulation of MDR1 and apoptosis." (PMID 25128483, 2014). "MiR-27a modulated MDR1/P-glycoprotein expression in human ovarian cancer cells by targeting HIPK2 and could reverse the multidrug resistance of esophageal squamous cell carcinoma through regulation of MDR1 and apoptosis." (PMID 23240057, 2012). "The overexpression of miR-27a which by regulating the target gene of HIPK2, could regulate the expression of MDR1 and P-gp indirectly, which influence ovarian cancer resistant to paclitaxel." (PMID 25342041, 2014).
glioblastoma (8 papers, 2009 to 2024). The most malignant astrocytic tumor (WHO grade IV). "Downregulation of the HIPK2 inactivator SIAH1 significantly ameliorates temozolomide‐induced glioblastoma cell apoptosis." (PMID 38186203, 2024). "We showed in glioblastoma cells that therapeutically relevant doses (<50 μM) of TMZ are effective in activating the ATR/ATM-SIAH1/HIPK2-p53Ser46 axis and thus trigger apoptosis." (PMID 38068493, 2023). "Their silencing of HIPK2 in U87 (a glioblastoma (GBM) cell line) decreased the cells proliferation rate." (PMID 19603027, 2009). "It is interesting that the inhibitors of HIPK2 and SIAH1 are often overexpressed in glioblastoma, which would impede activation of HIPK2 after DNA damage." (PMID 38068493, 2023). "The pathway of HIPK2 activation in general and following TMZ in glioblastoma cells, including LN-229, has been described." (PMID 30925722, 2019). "We also showed that p53ser46 exerts a pro-apoptotic function as downregulation of HIPK2, the kinase responsible for this phosphorylation, attenuated significantly the level of apoptosis in TMZ-treated LN-229 glioblastoma cells." (PMID 30925722, 2019).
pancreatic cancer (8 papers, 2015 to 2024). "In the current study, we investigated how HIPK2 contributes to oncogenic KRAS-driven tumorigenesis in the onset of pancreatic cancer." (PMID 39342278, 2024). "In our study, we found that miR-222-3p was significantly upregulated in pancreatic cancer and acted as an oncogene to enhance glycolysis and proliferation by directly targeting HIPK2." (PMID 33122827, 2021). "Recent research has demonstrated that HIPK2 attenuates glycolysis in pancreatic cancer by regulating the ERK/c-myc axis." (PMID 33122827, 2021). "RT-PCR analyses of tissue arrays and tumor samples show that HIPK2-FL and HIPK2-S are expressed in normal human tissues in a tissue-dependent manner and differentially expressed in human colorectal and pancreatic cancers." (PMID 32093146, 2020). "To investigate the contribution of HIPK2 to oncogenic KRAS-driven tumorigenesis in the onset of pancreatic cancer, we first assessed the expression of HIPK2 in human PDACs by WB, employing highly specific anti-HIPK2 Ab previously validated on human HIPK2-null cells and tissue microarrays." (PMID 39342278, 2024). "LINC00261 can also be over-expressed in pancreatic cancer tissues by binding miR-222-3p to activate the HIPK2/ERK/c-myc pathway 43, which unmasked a new epigenetic and post-transcriptional regulatory mechanism that contributes to targeted therapy for pancreatic cancer." (PMID 37859697, 2023). "Interestingly, previous research has established that HIPK2 can inhibit glycolysis and proliferation of pancreatic cancer by attenuating ERK/c-myc axis activity." (PMID 33122827, 2021). "A recent study discovered the suppressive effects of HIPK2 on proliferation and glycolysis in pancreatic cancer via inhibition of the ERK/c-myc axis, which was validated in our study and improved our understanding of the signal transduction and functional significance of LINC00261." (PMID 33122827, 2021). "Here, we investigated whether HIPK2 contributes to oncogenic KRAS-driven tumorigenesis in vivo, in the onset of pancreatic cancer." (PMID 39342278, 2024).
diabetic nephropathy (7 papers, 2016 to 2024). "For instance, it is found that HIPK2 level was improved in HG-treated mouse glomerular mesangial cells in a diabetic nephropathy research." (PMID 37710299, 2023). "The HG-increased expression of HIPK2 was also observed in glomerular mesangial cells (GMCs) of a mouse model of diabetic nephropathy (DN)." (PMID 37345014, 2023). "HIPK2 expression has been shown to be remarkably upregulated in kidneys of patients with HIV-associated nephropathy, diabetic nephropathy and severe IgA nephropathy." (PMID 29208636, 2018).
hepatocellular carcinoma (7 papers, 2016 to 2024). A malignant tumor that arises from hepatocytes. "It is reported that HIPK2 enhances autophagy in hepatocellular carcinoma cells, primary hepatocytes, and spinal cord injury tissues." (PMID 38186203, 2024). "In hepatocellular carcinoma, HMGBI promotes ubiquitination and degeneration of HIPK2, which results in autophagy induction and tumor progression." (PMID 37268944, 2023). "In human hepatocellular carcinoma (HCC) or other cell lines, under hypoxic conditions, WSB1 binds and mediates degradation of HIPK2." (PMID 27542736, 2016). "The balance between HIPK2 and HIF-1 in angiogenesis was recently confirmed in a study on hepatocellular carcinomas (HCC)." (PMID 36900356, 2023).
Hyperglycemia (7 papers, 2016 to 2024). An increased concentration of glucose in the blood. "The HIPK2 gene rarely mutates while HIPK2 protein can be inhibited by mechanisms activated by hypoxia or hyperglycemia, two conditions involved in tumor progression and also in fibrosis." (PMID 36831402, 2023). "Among these, HIPK2 activity has been found to be affected by hyperglycemia conditions and also influences the activity of PDX-1." (PMID 38326874, 2024). "Briefly, HIPK2 is activated by anticancer drugs or DNA damage and inactivated by hypoxia, hyperglycemia or micro (mi) RNAs." (PMID 39062921, 2024). "Recently, hyperglycemia was found to positively and/or negatively regulate HIPK2 activity, affecting not only cancer cell response to chemotherapy but also the progression of some diabetes complications." (PMID 37345014, 2023). "The low expression of the HIPK2 levels in DR is also in agreement with our recent study showing that hyperglycemia triggers HIPK2 degradation via HIF-1, increasing tumor progression." (PMID 36900356, 2023). "In the present study, we have shown that hyperglycemia promotes the degradation of HIPK2 in parte through ubiquitin ligase Siah2 downstream of a protein cascade including PP2A and HIF-1α, as summarized in the scheme." (PMID 27901482, 2017). "Interestingly, HIPK2 inhibition can be achieved in cancer cells by tumor hypoxia or by hyperglycemia, two conditions involved in both tumor progression and in fibrosis." (PMID 36831402, 2023). "Recent developments have suggested that HIPK2 deregulation by hyperglycemia may play a role not only in the chemoresistance of various cancer cell types but also in the progression of some diabetes complications, likely involving the same HIPK2-triggered molecular pathways." (PMID 37345014, 2023). "Taking advantage of the findings showing that hyperglycemia increases HIF-1α gene transcription and induces the HIF-1 transcriptional activity irrespective of the oxygen levels, in an in vitro study, it was shown that high glucose (HG) condition promotes the degradation of HIPK2." (PMID 37345014, 2023).
Nephropathy (7 papers, 2016 to 2024). A nonspecific term referring to disease or damage of the kidneys. "Recent advances in kidney fibrotic disease indicated that the protein expression of HIPK2 was significantly elevated in human HIV- associated nephropathy patients." (PMID 31915028, 2020). "Siah1 degrades homeo-domain interacting protein kinase 2 (HIPK2), a key molecule in the induction of kidney fibrosis and the epithelial-to-mesenchymal transition in various nephropathies such as human immunodeficiency virus (HIV)-associated kidney disease." (PMID 28859164, 2017). "As a signal transduction element, HIPK2 regulates molecular pathways that contribute to diabetes, nephropathy, idiopathic pulmonary fibrosis, cardiac disease and several cancers." (PMID 37268944, 2023). "Homeodomain‐interacting protein kinase 2 (HIPK2), which belongs to nuclear serine/threonine kinase, plays an important role in nephropathy." (PMID 38186203, 2024). "Homeodomain‐interacting protein kinase 2 (HIPK2), a nuclear serine/threonine kinase, plays an important role in nephropathy." (PMID 38186203, 2024). "Therefore, to further assess the mechanism of HIPK2 in mediating the response of RTEC injury, we examined the effect of BT173 in Pax8-HIPK2WT and Pax8-HIPK2KD mice in the setting of folic acid–induced nephropathy (FAN)." (PMID 32701510, 2020).
acute myeloid leukemia (6 papers, 2011 to 2023). Acute myeloid leukemia (AML) is a group of neoplasms arising from precursor cells committed to the myeloid cell-line differentiation. "HIPK2 is rarely mutated: the only HIPK2 mutations were reported by a study about human acute myeloid leukemias (AML) in which HIPK2 shows an aberrant nuclear distribution." (PMID 37345014, 2023). "Recently, two missense mutations of the HIPK2 gene have been identified in acute myeloid leukaemia (AML) and in myelodysplastic syndrome (MDS), a pre-leukaemia syndrome." (PMID 21698151, 2011). "Finally, in an in vitro study, the leukemogenic fusion protein CBF-β-SMMHC, which is associated with the development of acute myeloid leukemia (AML), was found to delocalize HIPK2 into filamentous structures in the cytoplasm, probably interfering with the tumor-suppressor function of HIPK2." (PMID 37345014, 2023). "Furthermore, Hipk2 has been identified as a potential drug target in treating Acute Myeloid Leukemia, which is due to activated JAK/STAT signaling." (PMID 31891940, 2019).
Sepsis (6 papers, 2018 to 2024). Sepsis is defined as life-threatening organ dysfunction caused by a dysregulated host response to infection. "Notably, mice deficient in Hipk2 are more susceptible to cecal ligation and puncture (CLP)-induced sepsis, as HIPK2 can bind to and phosphorylate histone deacetylase 3 (HDAC3), inhibiting its enzymatic activity." (PMID 39234245, 2024). "As CLP animal model is regarded as a better choice to simulate sepsis development in the clinic, we investigated the molecular mechanisms underlying the protective effect of HIPK2 on CLP-induced sepsis, devoting our attention to the mechanisms regulating autophagy." (PMID 30154452, 2018). "HIPK2 overexpression reduced the sepsis-mediated increase in calpain 1 and cleaved Atg5 levels but did not affect mTOR levels." (PMID 30154452, 2018). "In the present study, HIPK2 overexpression significantly enhanced the increased expression of the Atg12-5 complex and restored the reduced Atg3 expression in mice with sepsis-induced liver injury." (PMID 30154452, 2018). "Here, we investigated the roles of homeodomain-interacting protein kinase 2 (HIPK2) in the molecular mechanism of sepsis-induced liver injury." (PMID 30154452, 2018). "HIPK2 overexpression significantly downregulated the increased Ca2+ concentrations in mice with sepsis-induced liver injury." (PMID 30154452, 2018). "In conclusion, HIPK2 protected the liver from sepsis-induced injury through calpain 1-mediated autophagy." (PMID 30154452, 2018). "We analysed hepatic HIPK2 expression to initially examine the alterations in HIPK2 expression during sepsis." (PMID 30154452, 2018). "In vivo studies demonstrated that HIPK2-deficient mice are more susceptible to lipopolysaccharide (LPS)-induced endotoxemia and cecal ligation and puncture (CLP)-induced sepsis, with increased serum concentration of proinflammatory IL-6, IL-1β and TNF-α cytokines." (PMID 39062921, 2024). "Interestingly, in a mouse model of sepsis, HIPK2 overexpression has been shown to protect hepatocytic cells from injury by activating calpain-mediated autophagy." (PMID 36831402, 2023). "Indeed, overexpression of homeodomain‐interacting protein kinase 2 (HIPK2) attenuates sepsis‐mediated liver injury by reducing the activity of calpain‐1." (PMID 33473299, 2021). "Thus, HIPK2 overexpression ameliorated liver injury by restoring the autophagic flux in the livers of mice with sepsis." (PMID 30154452, 2018). "In conclusion, HIPK2 overexpression may improve sepsis-induced liver injury by restoring autophagy and thus might be a promising target for the clinical treatment of sepsis." (PMID 30154452, 2018). "Moreover, several anti-inflammatory drugs significantly increased the levels of the HIPK2 protein and mRNA by activating the promoter of the HIPK2 gene and by maintaining the stability of the 3′-UTR, confirming that HIPK2 is a target for sepsis treatments." (PMID 30154452, 2018). "Furthermore, staining for the LC3-II protein was significantly increased upon overexpression of HIPK2, and LAMP-2 expression was restored by overexpression of HIPK2 in the livers of mice with sepsis." (PMID 30154452, 2018). "These compounds significantly increased the levels of the HIPK2 mRNA and protein by regulating promoter activity and the stability of the 3′-UTR of the HIPK2 gene, indicating that HIPK2 might be a common and promising target for sepsis treatment." (PMID 30154452, 2018). "Moreover, the interaction of HIPK2 with calpain 1 was reduced in mice with sepsis-induced liver injury, and the interaction of HIPK2 with calmodulin was enhanced in septic mice." (PMID 30154452, 2018). "HIPK2 may inhibit calpain 1 activity and expression under normal conditions by interacting with calpain 1, and in response to sepsis, HIPK2 dissociates from calpain 1 and then interacts with calmodulin to decrease Ca2+ levels." (PMID 30154452, 2018).
Sepsis (continued). "Compared with that in the sepsis group, the 16-day survival rate of the Ad-HIPK2-treated sepsis group was improved (p < 0.05), indicating that the pretreatment of mice with Ad-HIPK2 before CLP significantly decreased lethality compared to that in animals with CLP-induced sepsis." (PMID 30154452, 2018). "Based on this premise, the 16-day survival rate was 16.7% (5 of 30 mice) in the CLP-induced sepsis group, 60.0% (18 of 30 mice) in the Ad-HIPK2-injected sepsis group, 6.67% (2 of 30 mice) in the Ad-shHIPK2-injected sepsis group and 100% in the control group (30 mice)." (PMID 30154452, 2018). "Consequently, HIPK2 overexpression may restore autophagosome–lysosome fusion in mice with sepsis-induced liver injury." (PMID 30154452, 2018). "However, the precise effects of HIPK2 on autophagy and sepsis-induced liver injury remain unclear." (PMID 30154452, 2018). "Based on these data, HIPK2 may inhibit calpain 1 activity under normal conditions by interacting with calpain 1, and in response to sepsis, HIPK2 dissociates from calpain 1 and then interacts with calmodulin to decrease Ca2+ levels, resulting in attenuation of sepsis-induced liver injury." (PMID 30154452, 2018). "However, the precise mechanisms by which HIPK2 regulates autophagy and sepsis remain unclear." (PMID 30154452, 2018). "HIPK2 overexpression increased the level of the Atg7 protein, which was not affected by CLP-induced sepsis, suggesting that HIPK2 overexpression promotes phagophore expansion and increases mature autophagosome formation in sepsis." (PMID 30154452, 2018). "Furthermore, Atg7 expression was not changed by CLP-induced sepsis, while the levels of this protein were increased upon HIPK2 overexpression." (PMID 30154452, 2018). "In addition, neither HIPK2 overexpression nor sepsis altered the level of the Beclin-1 protein." (PMID 30154452, 2018). "However, Beclin-1 expression was not changed by sepsis or HIPK2 overexpression." (PMID 30154452, 2018). "Thus, HIPK2-mediated autophagy is likely independent of Beclin-1 in sepsis." (PMID 30154452, 2018).